FOXP3 (forkhead box P3)
Diseases named in the same sentence as FOXP3 in open-access papers (continued):
Sharing a sentence is not in itself a finding about the gene and the disease.
tumor (continued). "There is increasing evidence that the expression of FoxP3 can also be detected in tumor cells." (PMID 37569676, 2023). "Although studies using the PROTACs in targeting Tregs are very limited, we believe that this innovative approach holds great promise in drug development, offering a precise means of modulating cellular processes by selectively eliminating Foxp3, with potential in anti-tumor immunity." (PMID 37936703, 2023). "However, the CD4+FoxP3+ Tregs density around S15+ TAMs was significantly higher than that around S15+ tumor cells." (PMID 37674198, 2023). "Using a preclinical mouse model of B16-F10 melanoma overexpressing IDO1 (B16IDO), authors demonstrated that IDO-expressing tumors have marked increases in Treg frequency and upregulated expression of FoxP3 in tumor infiltrating CD4+ T cells compared to B16WT-tumor bearing mice." (PMID 37876966, 2023). "The cross-G function—a form of probabilistic nearest neighbour analysis—was used to demonstrate shorter OS for patients with CD4+ forkhead box P3-positive (FoxP3+) Treg cells and tumour cells in close proximity (hazard ratio (HR) 1.52, 95% confidence interval [95%CI] 1.11–2.07 and p = 0.009)." (PMID 37835491, 2023). "Interestingly, key factors known to induce immune evasion in tumor microenvironment, namely Foxp3 + (marker for T regulatory cells-Treg) and Il-17A were significantly increased in the esophagus of IL-1β transgenic mice compared to wild type littermates." (PMID 37543673, 2023). "FOXP3 was found to have associations with DTC aggressiveness and tumor diameter." (PMID 37798795, 2023). "Foxp3 positive Treg, particularly terminally differentiated effector Treg cells, plays a crucial role in tumor immune evasion, suppressing immune recognition and diminishment and ensuring tumor development and metastasis." (PMID 37520520, 2023). "We observed that the FOXP3 + /CD8 + ratio fluctuated with tumor cell density." (PMID 36932390, 2023). "Forkhead box protein P3 (FoxP3) primarily functions as the master regulator in regulatory T cells (Tregs) differentiation, but its high level of expression has also been found in tumor cells recently." (PMID 37569676, 2023). "Multiplex immunohistochemistry staining of TILs (CD4, CD8, Foxp3, and PD-1) and immunohistochemical staining of CK and PD-L1 in the tumor and stroma was performed in tumor specimens of 107 NSCLC patients and correlated with clinical outcomes, as a single-center retrospective study." (PMID 36662367, 2023). "The lack of association between PD-1/FOXP3 with IDH1 mutational status of the tumor is probably one of the most fascinating findings of our study, which suggests that only a highly select subset of patients will benefit from combinatorial therapeutic options." (PMID 37621817, 2023). "FOXP3+ Tregs are responsible for maintaining immune tolerance, which can prevent allergic and other kinds of autoimmune diseases as well as inhibit the anti-tumor immune responses." (PMID 38077386, 2023). "Tregs overexpress FoxP3, a transcription factor associated with the up-regulation of CTLA-4 on the cell surface; CTLA-4 binds to CD80 expressed by antigen-presenting cells and inhibits cytotoxic T-cell activation, contributing to tumor development." (PMID 37324191, 2023). "These differentiated CD4+ T subsets, characterized by specific transcription factors, exert a broad range of immune responses in TME; TH1 (T-bet), TFH (BCL6), and TH9 cells are associated with antitumor activity, while TH2 (GATA3), TH17 (RORt), Tregg (FOXP3) cells promote tumor growth." (PMID 36672677, 2023). "However, CD3+CD8+ tumor-infiltrating T lymphocytes (TIL) correlate with better survival, whereas CD4+Foxp3+ TIL is associated with a poorer prognosis." (PMID 37444550, 2023). "The authors hypothesised that the presence of immunosuppressive FoxP3+ Treg cells in the TME may be related to the inhibition of a tumour-specific cytotoxic T-cell response." (PMID 37958391, 2023).
tumor (continued). "Interestingly, FOXP3 is also expressed in various cancer cells and plays a complex role in tumor development." (PMID 37868998, 2023). "Although neither GO-Y022 treatment nor 2DG demonstrated a minor effect on the stability of Foxp3+ Tregs in vitro, combined treatment with GO-Y022 and 2DG could affect the Foxp3+ Treg generation and stability in the tumor microenvironment." (PMID 36814928, 2023). "In addition, we evaluated the prevalence of tumor-infiltrating FOXP3+ Tregs within CD4+ T cells and tumor-associated macrophages (TAMs) by flow cytometry." (PMID 37906252, 2023). "We evaluated the tumor intrinsic effects of Foxp3 in MDA-MB-231 and MDA-MB-468 human TNBC cells." (PMID 37766222, 2023). "Moreover, LAG3 also helps maintain CD8+ T cells in a tolerogenic state and has been reported to play an issue role in CD4+CD25+Foxp3+Tregs suppressive function, thus favouring the escape of the tumour from immune surveillance in various human cancers." (PMID 36980527, 2023). "To further validate the relationship between FoxP3 expression level and the patients’ clinicopathological characteristics, we performed FoxP3 immunohistochemistry (IHC) in a ccRCC tissue microarray, including 90 tumor tissues and their paired 90 adjacent normal kidney tissues." (PMID 37569676, 2023). "The FOXP3+/CD8+ ratio increased significantly in the inner tumor areas (p = 0.002)." (PMID 36900270, 2023). "Treg cells are FOXP3-positive CD4+ T cells strongly inhibiting anti-tumor immune responses." (PMID 36831498, 2023). "Further study of specific lymphocyte subpopulations, such as FOXP3+, macrophages and T-reg lymphocytes, among others, could provide more insights into the clinical impact of the immune response in this tumor subtype." (PMID 37345183, 2023). "Furthermore, tumor‐induced PMN‐MDSCs inhibit TGF‐1‐mediated CD4+CD25+Foxp3+ Treg generation via ROS and indoleamine 2,3‐dioxygenase." (PMID 37382257, 2023). "On the contrary, inhibition of EZH2 may impair Foxp3 expression, reduce the suppressive activity of Tregs, reshape the tumor microenvironment, enhance CD8 and CD4 effector T cell recruitment and function, and thus enhance antitumor immunity." (PMID 37909018, 2023). "We also identify specific subtypes of stromal and immune cells critical to the formation of the pro-tumor microenvironment in metastatic lesions, including RGS5+ cancer-associated fibroblasts, CCL18+ lipid-associated macrophages, S100A8+ neutrophils and FOXP3+ regulatory T cells." (PMID 37612267, 2023). "It was reported by us and others that TNFR2 could be expressed by mouse antigen-experienced CD4+Foxp3- conventional T cells, including those in the tumor environment, we thus firstly analyzed TNFR2 expression by subsets of cells in CD4 T cell metaclusters." (PMID 36865537, 2023). "By visual inspection, we could also identify tumor cells that were double stainedfor cytoplasmic cytokeratin and nuclear FOXP3." (PMID 36880147, 2023). "STAT3 and STAT5 bind to a CNS in the FOXP3 promoter in tumor-infiltrating Tregs." (PMID 36816749, 2023). "Furthermore, when we analyzed the transcriptomic data from TNBC subtype BRCA biopsies deposited in TCGA, we found that tumor expression of Foxp3 positively correlated with the expression of MMP-2 and MMP-9." (PMID 37766222, 2023). "FoxP3 was upregulated in TIL after co-culture with CIITA-expressing syngeneic tumor cells (PGB1) as compared to co-cultures with the corresponding wildtype tumor cells (p = 0.04)." (PMID 38201622, 2023). "The increase in TILs in proportion to the degree of infiltration represents a natural defense process of the immune system, and the accumulation of inefficient Foxp3+ T cells may suppress tumor immunity and promote tumor progression." (PMID 37958412, 2023).
tumor (continued). "Furthermore, specific features within the immune microenvironment become evident, highlighting a significant reduction in FoxP3+ T cells spanning the entire tumor and a notable increase in the proportion of M2-polarized macrophages positioned within the tumor." (PMID 38292482, 2023). "However, in a study on PDAC, deletion of α-SMA+CAFs promotes tumor progression by increasing the number of CD4+ FOXP3+ Treg cells in tumors, suggesting that this subset has an important anticancer role in PDAC." (PMID 36759842, 2023). "The increase of intra-tumor FOXP3+ Treg cells caused by BF BSHhigh colonization was partially reversed by blocking CCL28, confirming a vital role for CCL28 in recruiting intra-tumor FOXP3+ Treg cells during CRC progression." (PMID 36765047, 2023). "Collectively, these results show a significantly higher infiltration with CD8 + TILs in BAP1- or PTEN-mutated ccRCCs both at the invasive margin and in the tumor periphery, while counts for CD4 + or FOXP3 + cells were found to depend more on the histological subtype than the mutational status." (PMID 36562826, 2023). "In addition, N-809 reduced the frequency of immunosuppressive regulatory T cells (defined as CD4+ FoxP3+ T cells) in the tumor environment." (PMID 37616311, 2023). "Tumor-infiltrating lymphocytes expressing TIGIT were correlated with high densities of CD45RO+ T cells; TIGTI+CD8+ T cells were associated with high infiltration of CD3+CD45RO+FOXP3+." (PMID 37649613, 2023). "However, in the IL34-OC+Foxp3-anti group, the tumor volume was significantly smaller than in the IL34-OC+IgG group, and the number of lung metastatic foci was significantly lower." (PMID 38081923, 2023). "Similarly, knocking down galectin-1 expression in 4T1 cells led to a diminished proportion of CD4+CD25+Foxp3+ Treg cells within the tumor microenvironment as well as peripheral immune organs." (PMID 37047471, 2023). "Interestingly, the tumors of PF patients showed a significant increase in stromal CD3+, GZMB+, FOXP3+, and CD11c+ cells compared with the tumor area." (PMID 37349318, 2023). "FAP+CAFs have also been associated with the recruitment of regulatory FOXP3+-T lymphocytes, and in agreement with this, we find that the decrease in regulatory T cells we observe in the TME of tumours from Snail1ME-KO mice favours an anti-tumourigenic phenotype." (PMID 37516803, 2023). "Furthermore, the HCC tumours were found to cultivate a suppressive immune system, as demonstrated by the enrichment of FoxP3+ cells (5.2% vs. 3.1%) and depletion of cytotoxic CD8+ cells (0.9% vs. 3.2%), which is in line with other studies." (PMID 37048147, 2023). "Examination of tumor tissue sections after anti-PD1 therapy demonstrated a co-localization of mast cells and forkhead box P3 (FOXP3)+ Treg cells and this evidence may be associated with a down-modulation of HLA class I on tumor cells." (PMID 37038035, 2023). "Our preliminary data might suggest that FoxP3 could modulate the RCC tumor microenvironment and promote RCC aggressiveness." (PMID 37569676, 2023). "In addition to the PD-L1/PD-1 pathway, other immune cells (CD8, CD4, FoxP3) appear to be exciting as tumor markers in the overall context." (PMID 37932810, 2023). "The role of FOXP3 in tumor cells is, however, controversial." (PMID 36672296, 2023). "Protein targets associated with B cells (CD20), NK cells (CD56), macrophages (CD68), and regulatory T cells (PD-1, FOXP3) were most differentially expressed in CD45+ segments within ‘immune-rich cancer cell islet’ regions of the tumor (cf. ‘surrounding stromal leukocyte’ regions)." (PMID 37046826, 2023). "However, evaluating the sub-populations, we did not observe significant differences in the frequency of CD8+ T cells or CD4+ FoxP3+ Tregs in the tumor." (PMID 36920329, 2023). "MTE treatment reduced TGF-β1 expression within the tumor cells and FOXP3 expression in the TILs." (PMID 37649480, 2023).
tumor (continued). "However, despite close proximity to CD8+ killer T cells, dormant tumor cells themselves support early accumulation of protective FoxP3+ T regulatory cells (Tregs), which can be targeted to reduce tumor burden." (PMID 37847565, 2023). "Collectively, the results from our cell lines and TCGA ccRCC RNA-seq results indicated that FoxP3 might play a pro-oncogenic role in ccRCC by activating immune-related pathways and by recruiting more Treg cells into the tumor microenvironment." (PMID 37569676, 2023). "Furthermore, it has been found that the frequency of IL-17+ T cells was inversely correlated with tumor size, while the frequency of Foxp3+T cell in tumor infiltrates was positively correlated with the TNM stage." (PMID 37373022, 2023). "Collectively, the elevated expression of Eomes, Tbet, and Foxp3 suggest an activated but potentially functionally-exhausted T-cell phenotype which may contribute to attenuated tumor clearance in S47 mice." (PMID 37441266, 2023). "Since PTPN2 promotes FoxP3/Treg stability, the KDDN results suggest that JGT may inhibit immunosuppressive Foxp3 cells in the tumor microenvironment." (PMID 36980301, 2023). "In various solid tumours, PD-L1 expression has been found to be related to the density of certain subtypes of ICs, including CD4+ T helper cells (Ths), CD8+ cytotoxic T cells (CTLs), FOXP3+ regulatory T cells (Tregs), and CD163+ tumour-associated macrophages (TAMs)." (PMID 38175373, 2023). "Moreover, these TAMs potentiated T cell dysfunction, including increased differentiation to forkhead box P3-positive (FOXP3+) regulatory T cells and impaired anti-tumor activity of CD8+ T cells." (PMID 38022518, 2023). "For example, FOXP3 interaction with NFAT or NFκB regulates anti-tumour immunity." (PMID 36973425, 2023). "As explained, CD4 + Foxp3 + Tregs are potent immunosuppressive cells that may help tumor progression." (PMID 37221555, 2023). "Similarly, the proportion of CD4+ T helper 1 (TH1) effectors increased relative to regulatory CD4+ TREG cells in intermediate (D14) and late stage (D21) tumours (decreasing CD4+FoxP3+/CD4+T-bet+ ratio)." (PMID 37153625, 2023). "Collectively, these data suggested that the expression level of FoxP3 was higher in tumor tissues, and that it might be positivity correlated with the ccRCC stages." (PMID 37569676, 2023). "In this study, we evaluated FOXP3 expression based on intensity in the tumor center and invasive front and found that infiltration of cells with weak (low-intensity) FOXP3 expression was significantly higher in MCPyV-positive MCC cases than in MCPyV-negative MCC cases." (PMID 37573372, 2023). "However, the level of Foxp3 expression in the tumor was lower at day 7 for the CA + CS/IL-12 group compared to CA alone." (PMID 37190138, 2023). "However, mice treated with Ad.P60 exhibited a significant lower number of tumor infiltrating Tregs (CD45+CD4+Foxp3-GFP+) than those administered with Ad.dT." (PMID 37766222, 2023). "Furthermore, tumor-infiltrating Tregs expressing high levels of Foxp3+ secrete extreme amounts of immunosuppressive cytokines, thereby additionally suppressing anti-tumor activity." (PMID 37509517, 2023). "Interestingly, our gene expression data also revealed reduced levels of Foxp3 (a gene typically expressed by Tregs) in the tumor following C215Fab-SEA treatments." (PMID 36967382, 2023). "In non-HPV-associated HNSCC tumours, a better OS was noted in patients with high Foxp3+ TILs (HR 0.80; 95% CI: 0.70–0.92) and similar dependences were seen for DFS (HR 0.77; 95% CI: 0.57–1.02) and LRC (HR 0.92; 95% CI: 0.81–1.04)." (PMID 36980527, 2023). "Such an increased ratio could evolve from increased CD8+ T cell tumor infiltration or reduced presence of FoxP3+ Tregs." (PMID 36920329, 2023). "FOXP3+ TILs were significantly more abundant in the inner tumor areas (p = 0.0006)." (PMID 36900270, 2023). "FOXP3 regulates Tregs functions, and suppresses anti-tumor immunity." (PMID 36721212, 2023).
tumor (continued). "And we further stained the spleen tissue of subcutaneous tumor-bearing mice with a Foxp3 antibody." (PMID 37723552, 2023). "In large-cell lung cancer, FoxP3 could promote the tumor growth and metastasis by activating the Wnt/β-catenin signaling pathways." (PMID 37569676, 2023). "Here, we aimed to better understand the tumor intrinsic effects of Foxp3 in BRCA cells." (PMID 37766222, 2023). "FOXP3 expression in CD8 T cells favored their accumulation within the tumor." (PMID 36045586, 2023). "However, it has also been proposed that tumor cells expressing Foxp3 can activate PD-L1 expression and inhibit CD8+ T cell activity, maintaining an immunosuppressive TME." (PMID 37766222, 2023). "Crosstalk between Foxp3+ Tregs and macrophages responsible for the failure of immuno‐surveillance and specific targeting of related cascades may reactivate anti‐tumor immunity in EC." (PMID 36226375, 2023). "The stromal FoxP3+ Tregs may hinder inflammatory anti‐microbial activity allowing progression of the tumor, while intraepithelial FoxP3+ Tregs may inhibit, possibly directly contacting with tumor cells, antitumoral immune activity." (PMID 37537787, 2023). "Recruitment of Foxp3+ T cells in HCC tumor tissue indicated development of HCC." (PMID 38090482, 2023). "For example, tumor-infiltrating FOXP3+ regulatory T cells (Tregs), whose canonical function is immunosuppressive, have been shown to be associated with reduced survival and tumor recurrence in patients with GBM, while the opposite is true for cytotoxic CD8+ T cells." (PMID 36828374, 2023). "Upregulation of CCL5 enables tumor FOXP3+ Treg cell aggregation in PDAC." (PMID 37529035, 2023). "Furthermore, TGF-2 and IL-10 are among the cytokines FoxP3 regulates, and thus promotes tumor cells to evade immunity and to deteriorate further." (PMID 37531206, 2023). "Colocalization of Tregs and Foxp3-negative T-cells in the primary tumor was also statistically significantly negatively associated with rCR." (PMID 37794508, 2023). "Outcomes included immunohistochemistry of dendritic cells (DCs), M1 and M2 macrophages, T-helper cells (Th1) (CD4+), cytotoxic T- lymphocytes (CTL) (CD8+), T-regulator cells (T-reg) (FoxP3+) and Fas Ligand activated CTLs (Fas-L+) in the periablational rim and untreated index tumor." (PMID 37883367, 2023). "Tumor suppressor function of FOXP3 was partially inhibited by miR-146a/b negative regulators." (PMID 37689738, 2023). "In the IM, FOXP3 in Treg cells can combine with T-bet, a key transcription factor in Th1 cells, due to external environmental stimuli, specifically enhancing the immunosuppressive function of Tregs, which in turn promotes tumor progression." (PMID 37753092, 2023). "FOXP3 was also shown to have a suppressive function and promote tumour growth." (PMID 37761018, 2023). "Moreover, tumor-derived galectin-1 was demonstrated to attenuate the expansion of the CD4+CD25+FOXP3+ Treg cells in human Hodgkin lymphomas." (PMID 37047471, 2023). "Metformin decreases infiltration of FOXP3+ T regulatory cells in intratumor regions, increases CD8+ cytotoxic T cell infiltration in the peritumoral leading edge stroma, and increases the CD8/FOXP3 ratio both in the tumor and leading-edge stroma of primary HNSCC tumors." (PMID 37344841, 2023). "In addition, increased Foxp3 gene expression and Foxp3+ Tregs accumulation were also observed in the regions near the tumor metastasis proximity site, as well as higher STAT3 expression." (PMID 36226375, 2023). "Moreover, we found that expression levels of IL10, TGFβ1 and FOXP3 in tumour B cells from untreated CLL B patients were predictive of disease progression." (PMID 36973425, 2023). "The expression of FOXP3 in tumor cells has been linked to poor prognosis inseveral cancers, and as far as we know, expression of FOXP3 in prostate tumorcells has not yet been investigated." (PMID 36880147, 2023).